EGFR (epidermal growth factor receptor)
Diseases named in the same sentence as EGFR in open-access papers (continued):
Sharing a sentence is not in itself a finding about the gene and the disease.
non-small cell lung carcinoma (continued). "BLU-945 is one of the fastest advancing fourth-generation EGFR inhibitors in research, and BLU-945 alone or in combination with oxitinib showed early signals of clinical activity and was well tolerated in a large number of pre-treated EGFR-mutated non-small cell lung cancer patients." (PMID 39404930, 2024). "Osimertinib is a tyrosine kinase inhibitor of the epidermal growth factor receptor (EGFR) that is used for first-line therapy in EGFR mutated non-small cell lung cancer (NSCLC) based on the results of the randomized FLAURA trial (ClinicalTrials.gov number NCT02296125)." (PMID 38539415, 2024). "In this phase 3 study (ClinicalTrial.gov: NCT04028778), 315 patients with treatment-naïve, EGFR-mutated, advanced non-small cell lung cancer (NSCLC) were randomized (1:1) to receive anlotinib or placebo plus gefitinib once daily on days 1–14 per a 3-week cycle." (PMID 39134529, 2024). "However, the efficacy of ICIs in patients with non-small cell lung cancer (NSCLC) harboring epidermal growth factor receptor (EGFR)-sensitive mutations (exon 19 deletion/exon 21 L858R mutation) is disappointing and usually results in severe adverse events." (PMID 38378870, 2024). "Interestingly, CAGE regulates autophagy and the response to anticancer drugs by binding with Beclin1 in non-small cell lung cancer cells with EGFR mutations using an in vitro model." (PMID 37735252, 2023). "MET amplification has been reported in 5–26% of patients with non-small-cell lung cancer (NSCLC) after resistance to epidermal growth factor receptor (EGFR) inhibitor, with MET exon 14 skipping mutation in approximately 3% of NSCLC, and c-MET overexpression in about 35–72% of NSCLC." (PMID 37041472, 2023). "Therefore, osimertinib is the preferred first-line treatment of advanced EGFR-mutated non-small-cell lung cancer (NSCLC)." (PMID 37908018, 2023). "NEJ009 is the first phase III study to evaluate the efficacy of a combination of EGFR-TKI plus platinum combination therapy, used in conjunction with standard EGFR-TKI monotherapy for the treatment of advanced non-small-cell lung cancer harboring EGFR mutations." (PMID 37390279, 2023). "Such integration may be important if there is a benefit to upfront EBRT, even in the setting of systemic therapies with CNS penetration, as suggested by one study in EGFR-mutated non-small cell lung cancer." (PMID 39355023, 2023). "EGFR mutations are present in approximately 15% of patients with non-small-cell lung cancer." (PMID 36770773, 2023). "EGFR mutations (particularly T790M and L858R double mutation) are known as a major cause of EGFR signaling hyperactivation and EGFR-targeted drug acquired resistance in many cancers, especially in non-small cell lung carcinoma (NSCLC)." (PMID 37528485, 2023). "Non-small cell lung cancer (NSCLC) harboring activating mutations in the epidermal growth factor receptor (EGFR) kinase domain may be treated with EGFR–tyrosine kinase inhibitors (TKIs), including erlotinib and gefitinib." (PMID 38033496, 2023). "The first platform combining CRISPR-deactivated Cas9 (dCas9), magnetic beads, and allele-specific qPCR was set up to test the most common EGFR mutations including exon 19 deletion, T790M, and L858R in cfDNA samples of patients with non-small cell lung cancer (NSCLC)." (PMID 38188023, 2023). "Finally, a potential cross talk between ACE2 and EGFR was also described in non-small-cell lung cancer cells, where mutations in EGFR correlated with an increased expression of ACE2." (PMID 37402592, 2023). "Furmonertinib (alflutinib, AST2818) is an irreversible EGFR TKI approved in China in 2021 to treat patients with locally advanced or metastatic non-small cell lung cancer (NSCLC) with confirmed EGFR T790M mutations, whose disease has progressed during or after EGFR TKI therapy." (PMID 37762275, 2023).
non-small cell lung carcinoma (continued). "Epidermal growth factor receptor (EGFR) mutation represents the most frequent driver-gene alteration in non-small cell lung cancer (NSCLC), and 90% of EGFR mutations involving a deletion within exon 19 (19del) or a leucine-to-arginine substitution in exon 21 (L858R)." (PMID 37635242, 2023). "Currently, all cancer types effectively treated by targeted therapy appear to be mono-driver cancers, such as chronic myeloid leukemia dependent on BCR-Abl, non-small cell lung cancer dependent on mutated EGFR, and gastrointestinal stromal tumors dependent on c-Kit." (PMID 38136350, 2023). "To test the concept of what we term Synthetic Antigen Receptor (SAR)-MSCs, we functionalized MSCs with Ab, targeting the epidermal growth factor receptor (EGFR), whose overexpression is implicated in the pathogenesis of several malignancies, including non-small-cell lung cancer (NSCLC)." (PMID 37376189, 2023). "In patients with non-small cell lung cancer, 95.84% of the pharmaceutical antineoplastic expenditure was explained by four therapeutic groups: immunotherapy (33.74%), drugs targeting EGFR-activating mutations (28.36%), pemetrexed (22.16%), and ALK tyrosine kinase inhibitors (11.58%)." (PMID 37754495, 2023). "Several epidermal growth factor receptor (EGFR) tyrosine kinase inhibitors have been developed and approved by the FDA for the treatment of non-small-cell lung cancer, but their efficacy may be compromised by drug resistance in EGFR-mutant variants." (PMID 36733714, 2023). "Therefore, the present study evaluated ctDNA during osimertinib administration as a second-line or more setting to identify the relationship between EGFR mutation levels and outcomes in patients with advanced non-small cell lung cancer (NSCLC)." (PMID 38012343, 2023). "In addition, in 384 patients with non-small-cell lung cancer, the incidence of brain metastases was 49.5% among patients with L858R EGFR-mutated cancer versus 27.3% among those with wild-type cancer." (PMID 36980614, 2023). "For instance, the epidermal growth factor receptor (EGFR) mutation may be seen in certain non-small cell lung cancers (NSCLCs)." (PMID 37895393, 2023). "The present study indicates that furmonertinib may be a first-line treatment option for patients with non-small cell lung cancer harboring EGFR ex20ins mutation." (PMID 38206746, 2023). "Patients with epidermal growth factor receptor (EGFR)-mutated non-small cell lung cancer (NSCLC) often develop resistance to current standard third-generation EGFR tyrosine kinase inhibitors (TKIs); no targeted treatments are approved in the osimertinib-relapsed setting." (PMID 37710001, 2023). "This method could concurrently enrich three hotspot EGFR mutations in tumor samples from non-small cell lung cancer (NSCLC) patients up to 20-fold and detect them by qPCR." (PMID 36674433, 2023). "Afatinib is approved for non-small cell lung cancer harboring EGFR mutations." (PMID 38154692, 2023). "Similarly, the overexpression of EGFR mRNA in circulation (isolated from peripheral blood) was linked to non-small cell lung cancer, pancreatic cancer and colon cancer." (PMID 37091783, 2023). "Our report also provides a comprehensive summary of the clinical and pathological features, as well as treatment strategies, for non-small cell lung cancer patients with concurrent epidermal growth factor receptor mutation and anaplastic lymphoma kinase rearrangement." (PMID 37705536, 2023). "Recently, local and targeted therapy combinations have shown promising results in treating non-small cell lung cancer, predominantly caused by the epidermal growth factor receptor and anaplastic lymphoma kinase gene mutations, suggesting the potential of these new treatment strategies." (PMID 38003982, 2023).
non-small cell lung carcinoma (continued). "Non-small cell lung cancer (NSCLC) patients with epidermal growth factor receptor (EGFR) mutation often obtain de novo resistance or develop secondary resistance to EGFR tyrosine kinase inhibitors (EGFR-TKIs), which restricts the clinical benefit for the patients." (PMID 37553597, 2023). "Additionally, due to the heterogeneity of tumors, wild epidermal growth factor receptor (EGFR) non-small cell lung cancer (NSCLC) promotes the resistance of mutated EGFR NSCLC to osimertinib by transferring wild EGFR to mutant NSCLC." (PMID 37907962, 2023). "However, the cost-effectiveness of all available first-line treatments for patients with advanced epidermal growth factor receptor (EGFR) mutated non-small cell lung cancer (NSCLC) is still uncertain." (PMID 35785198, 2022). "Epidermal growth factor receptor (EGFR) mutations were strongly correlated with the clinical benefit of EGFR-tyrosine kinase inhibitors (EGFR-TKIs) and the first druggable driver mutation in non-small-cell lung cancer (NSCLC) 1,2." (PMID 35430596, 2022). "Osimertinib targeting epidermal growth factor receptor (EGFR) mutations in patients with non-small cell lung cancer and intrathecal trastuzumab in HER2-positive breast cancer patients with LM have shown therapeutic efficacy with the median overall survival exceeding 13 months." (PMID 35677335, 2022). "The impact of an initial skeletal-related event (SRE) and denosumab adjuvant treatment on the survival outcome of epidermal growth factor receptor (EGFR)-mutated non-small cell lung cancer (NSCLC) patients with bone metastasis remains unclear." (PMID 35884531, 2022). "In particular, in 2016, the FDA approved the Cobas EGFR Mutation Test v2 (Roche Molecular Systems, Inc., Pleasanton, CA, USA) for the diagnosis of somatic activating mutations in the EGFR gene in the plasma of patients with non-small cell lung cancer." (PMID 35453902, 2022). "Non-small cell lung cancer patients would benefit from different generations of tyrosine kinase inhibitors, depending on the particular mutation identified from epidermal growth factor receptor (EGFR) mutation detection assays 3-6." (PMID 35154443, 2022). "We investigated this by extracting total intravesicular nucleic acid content from sEVs isolated from the conditioned cell medium of the human NCI-H1975 cell line containing the epidermal growth factor (EGFR) gene mutation T790M as a model system for non-small cell lung cancer." (PMID 36555692, 2022). "It has been reported that examining mutation of CTC levels in non-small-cell lung cancer (NSCLC) may be helpful in detecting heterogenic mutations in EGFR." (PMID 35127345, 2022). "EGFR gene is commonly mutated in non-small-cell lung cancer (NSCLC) patients." (PMID 36010677, 2022). "In the solid tumor space, adjuvant therapy with osimertinib targeting activating mutations in epidermal growth factor receptor (EGFR) in patients with completely resected, EGFR-mutated non-small cell lung cancer is another example of the successful targeting of molecular MRD that improves survival." (PMID 35804850, 2022). "Furthermore, we correlated HPV 16E6/18E6 expression and EGFR (membranous and nuclear) expression with the clinical association and their survival impact in a non-small cell lung cancer (NSCLC) cohort." (PMID 36358752, 2022). "In addition, non-small-cell lung cancer is usually characterized by the mutation of the epidermal growth factor receptor (EGFR), and the level of linoleic acid tends to increase significantly in cancer patients with more EGFR." (PMID 36144573, 2022). "In the FLAURA trial, the third-generation epidermal growth factor receptor (EGFR) tyrosine kinase inhibitor osimertinib prolonged PFS and OS compared with erlotinib or gefitinib as first-line therapy in patients with EGFR-mutated advanced non-small cell lung cancer (NSCLC)." (PMID 35099678, 2022). "Activation of EGFR is a major risk factor for non-small cell lung cancer (NSCLC)." (PMID 35280763, 2022).
non-small cell lung carcinoma (continued). "In addition, miR-30b was found to inhibit the EGFR pathway by targeting EGFR in non-small-cell lung cancer, thus causing inhibition of Bax and caspase-3." (PMID 35291564, 2022). "Amivantamab, a bsAb targeting EGFR and MET, was developed by Janssen Biotechnology and approved by the FDA in May 2021 for patients with non-small cell lung cancer (NSCLC) whose tumors have EGFR exon 20 insertion mutations." (PMID 36341333, 2022). "Furthermore, HER3-DXd (an ADCs targeting HER3) was found to be effective in EGFR-mutated drug-resistant non-small cell lung cancer." (PMID 36508072, 2022). "In addition, inhibition of β-catenin decreases stem cell-like properties and enhances anticancer effects of EGFR-TKIs in EGFR-mutated non-small-cell lung cancer." (PMID 35301287, 2022). "EGFR inhibitors (EGFRIs) target non-small cell lung cancer caused by mutations in the EGFR gene." (PMID 35372072, 2022). "Besides being a good radiosensitizer, niraparib enhanced the anti-tumor immune effects of radiation on EGFR-mutated non-small cell lung cancer as seen from clone formation and apoptosis assay." (PMID 35364771, 2022). "PCR-based cfDNA assays for oncogenic driver variants of genes such as EGFR in non-small cell lung cancer (NSCLC) and KRAS in colorectal cancer (CRC) showed high specificity (mean 96%) but only moderate sensitivity (mean 66%) when compared with tumor tissue assays, which are still the gold standard." (PMID 36141326, 2022). "Indeed, FAK, a very important cancer-promoting molecule in cancer, is involved in a variety of cancer signalling pathways, and αV-FAK has been demonstrated to be related to the resistance of EGFR mutated non-small-cell lung cancer." (PMID 35597804, 2022). "Non-small cell lung cancer (NSCLC) harboring somatic mutations in the tyrosine kinase domain of epidermal growth factor receptor (EGFR) represents a molecular subgroup of NSCLC requiring treatment with EGFR tyrosine kinase inhibitors (TKIs)." (PMID 35326725, 2022). "In the open-label, monocentric phase II trial (NCT00988169), the efficacy of the combination with erlotinib and AT-101 was investigated in patients with advanced non-small cell lung cancer who were treatment-naive, and had epidermal growth factor receptor activating mutations." (PMID 35215257, 2022). "In the present study, we analyzed ctDNA using the NOIR sequencing system in patients with non-small cell lung cancer (NSCLC) harboring EGFR T790M mutation to evaluate the therapeutic effect of osimertinib and behavior of tumor subclones during osimertinib treatment." (PMID 35941190, 2022). "About 10–30% of patients with non-small cell lung cancer (NSCLC) harbor mutations of the EGFR gene." (PMID 35742933, 2022). "Another study reported that non-small cell lung cancer patients with EGFR mutation and higher PD-L1 expression may benefit from PD-1 inhibitors." (PMID 35720326, 2022). "EGFR-mutated tumors represent a significant percentage of non-small cell lung cancer." (PMID 35454838, 2022). "To demonstrate that the visual barcodes and a signalome system can be readily applied to other cell lines we generated two more signalome cell lines using the PC9 EGFR-mutated non-small-cell lung cancer cell line and the SK-MEL-5 BRAF-mutated melanoma cell line." (PMID 35585055, 2022). "The in-frame deletion in exon 19 (19del; 49–72%) and one nucleotide substitution within codon 858 of exon 21 (L858R; 28–43%) are two predominant epidermal growth factor receptor (EGFR) alterations in non-small cell lung cancer (NSCLC), called “common mutations” or “classic mutations”." (PMID 35770100, 2022). "First, we report on a retrospective study investigating the effects of an alkaline diet on advanced or recurrent non-small cell lung cancer patients with epidermal growth factor receptor (EGFR) mutations, who were treated with EGFR-tyrosine kinase inhibitor (TKI)." (PMID 36185175, 2022).
non-small cell lung carcinoma (continued). "EGFR inhibition by monoclonal antibodies or small-molecule tyrosine kinase inhibitors (TKIs) has been approved for the treatment of tumor entities such as RAS wildtype colorectal cancers, squamous cell carcinoma of the head and neck (HNSCC), and EGFR mutated non-small-cell lung cancer (NSCLC)." (PMID 35453544, 2022). "However, for advanced non-small cell lung cancers (NSCLCs) harboring driver mutations such as EGFR or ALK mutations, immunotherapy exhibited impaired response compared to corresponding targeted therapies." (PMID 36123526, 2022). "In the last decade, the prognosis and treatment of non-small-cell lung cancer (NSCLC) have improved as a result of the discovery of epidermal growth factor receptor (EGFR) mutations, which are predictor markers for the response to tyrosine kinase inhibitors (TKIs)." (PMID 35565386, 2022). "In May 2021, the FDA approved amivantamab, developed by Janssen, for the treatment of EGFR-mutated non-small cell lung cancer." (PMID 36341333, 2022). "For instance, elevated TRIB3 links stress signals to induce breast cancer initiation and progression by supporting breast cancer stemness, and elevated TRIB3 is positively associated with epidermal growth factor receptor (EGFR) stability and non-small cell lung cancer (NSCLC) progression." (PMID 36555349, 2022). "Programmed cell death receptor ligand-1 (PD-L1) expression, KRAS (KRASm) and EGFR (EGFRm) mutations may influence non-small cell lung cancer (NSCLC) prognosis." (PMID 34413420, 2021). "This case indicated that non-small cell lung cancer patients harboring the EGFR E709_T710delinsD mutation could benefit from afatinib treatment, followed with almonertinib treatment, as a potential therapeutic strategy." (PMID 34178699, 2021). "Currently, several clinical trials that co-target MET are ongoing for EGFR mutated non-small cell lung cancer (NSCLC) patients who acquired resistance to osimertinib; these include savolitinib plus osimertinib (SAVANNAH) or tepotinib plus osimertinib (INSIGHT 2)." (PMID 33572269, 2021). "The discovery of EGFR mutations and ALK rearrangements also contributed to the development of a new scale of prognostic factors in patients with brain metastases of non-small cell lung carcinoma, taking into account the presence of EGFR mutations or ALK rearrangements." (PMID 33435596, 2021). "For advanced non-small cell lung cancer with epidermal growth factor receptor (EGFR) mutation positive, individualized treatment was conducted based on precise genotyping and dynamic monitoring, which can not only control the tumor, but also have mild toxic and side effects." (PMID 34157804, 2021). "A systematic review of 3381 somatic EGFR mutations detected in 12,244 patients with non-small cell lung cancer found that 71% of the EGFR mutations were seen in only a single case, suggesting that many of the reported EGFR mutations may be sequence artifacts." (PMID 34680867, 2021). "Up to 40% of patients with epidermal growth factor receptor (EGFR) mutation-positive non-small-cell lung cancer (NSCLC) may develop central nervous system (CNS) metastases throughout their disease." (PMID 34359582, 2021). "In non-small-cell lung carcinoma, EGFR-activating mutations were significantly associated with increased PD-L1 expression that could be downregulated by treatment with erlotinib." (PMID 33718186, 2021). "For example, the G1/EGFRm subgroup may represent a more promising target to EGFR inhibitors than the larger G1/EGFR↑ subgroup, similarly to non-small cell lung carcinomas with EGFR mutations." (PMID 34572759, 2021). "Local ablative therapy (LAT) may be beneficial for patients with epidermal growth factor receptor (EGFR) mutated non-small cell lung cancer (NSCLC) with oligo-residual disease after treatment with EGFR tyrosine kinase inhibitor (EGFR-TKI)." (PMID 34798865, 2021).